CNTF (ciliary neurotrophic factor)
Diseases named in the same sentence as CNTF in open-access papers (continued):
Sharing a sentence is not in itself a finding about the gene and the disease.
Obesity (24 papers, 2010 to 2025). Accumulation of substantial excess body fat. "We found that obesity is associated with increased CNTF hypothalamic signalling, whereas calorie restriction induced its reduction." (PMID 35585213, 2022). "The multiple quantile regression analysis confirmed the independent effect of obesity, alone or associated with diabetes, and gender on plasma CNTF levels; in addition, fasting insulin was positively associated with plasma CNTF, with higher levels in females." (PMID 35585213, 2022). "The CNTF pathway has been proposed as a target for the treatment of obesity associated with leptin resistance." (PMID 35316287, 2022). "Collectively, our findings suggest that HFD obesity is associated with an increase in hypothalamic CNTF signaling, whereas CR induces a reduction of CNTF signaling in the hypothalamus." (PMID 24409114, 2013). "However, its susceptibility to neutralizing anti-CNTF antibodies in patients hampered its use for treatment of human obesity and diabetes." (PMID 35316287, 2022). "Studies involving a higher number of selected patients may reveal circulating CNTF and/or CNTFRα as potential novel diagnostic and/or prognostic markers of obesity, diabetes and associated diseases." (PMID 35585213, 2022). "In conclusion, human obesity is associated with high plasma CNTF levels, which may have a role in counteracting obesity-induced tissue damage, inflammation and dysmetabolism." (PMID 35585213, 2022). "Notably, studies involving a higher number of selected patients may disclose circulating CNTF as a potential novel diagnostic and/or prognostic marker of obesity, diabetes and associated diseases." (PMID 35585213, 2022). "The CNTF derivate, Axokine, was protective against obesity and insulin resistance, but clinical development was halted by the emergence of CNTF antibodies." (PMID 38569939, 2024). "In both genders, CNTF levels correlated significantly and positively with obesity (BMI, WHR, leptin), diabetes (fasting insulin, HOMA index and HbA1c) and inflammation (IL-6 and hsCRP) indices." (PMID 35585213, 2022). "Collectively, these results demonstrate that human blood contains a higher number of molecules of CNTF than of CNTFRα and that free CNTF tends to increase in patients with obesity." (PMID 35585213, 2022). "Collectively, our findings indicate that circulating CNTF levels are upregulated in such patients and that they correlate with several clinical and/or haematological indices of obesity, inflammation and insulin resistance." (PMID 35585213, 2022). "AMPK also targets another anti-obesity hormone, ciliary neurotrophic factor (CNTF), a member of the cytokine family." (PMID 36386794, 2022). "Among them, CNTF is the cytokine attracting the strongest interest, due to its anti-obesity effect in animal models as well as in leptin-resistant obese patients." (PMID 31781039, 2019). "Collectively, our results show that CNTF exerts anti-obesity and anti-inflammatory effects also on human adipocytes." (PMID 31781039, 2019). "In recent years, gp130 receptor ligands, including ciliary neurotrophic factor (CNTF) and interleukin (IL)-6, have been shown to modulate energy balance and investigated as potential therapeutic targets for obesity and insulin resistance." (PMID 31013924, 2019). "Administration of ciliary neurotrophic factor (CNTF) to experimental animals exerts anti-obesity effects by acting on multiple targets." (PMID 31781039, 2019). "The ability of CNTF and its analogs to overcome leptin resistance in mouse models of obesity and in obese patients underscores its potential as an anti-obesity drug." (PMID 27445662, 2016). "CNTF, an anti-obesity, anti-diabetogenic cytokine, promotes the same effects in mice: reduced IDE expression in the liver, reduced insulin clearance, and improved insulin sensitivity through IR-AKT phosphorylation." (PMID 25822220, 2015).
Obesity (continued). "With the failure of leptin as anti-obesity therapy, recent research has focused on the gp130 receptor ligands, in particular CNTF, as potential therapeutic agents for obesity." (PMID 21937762, 2011). "However, whereas in women CNTF secretion was higher in the Obesity group, in men it was higher in group with obesity and diabetes." (PMID 35585213, 2022). "Collectively, these data show that obesity, with or without diabetes, is associated with increased circulating CNTF levels in both genders." (PMID 35585213, 2022). "Finally, the activation of endogenous CNTF signalling in obesity is supported by the higher CNTF/CNTFRα molar ratio found in these subjects, where a larger number of free circulating CNTF molecules are available to signal to CNTFRα-expressing target cells." (PMID 35585213, 2022). "In conclusion, endogenous CNTF signalling is activated in human obesity and may help counteract some adverse effects of obesity." (PMID 35585213, 2022). "The association between CNTF levels and obesity with or without diabetes was confirmed even when the multiple regression analysis was adjusted for fasting insulin and the interaction between fasting insulin and gender." (PMID 35585213, 2022). "In obesity, some types of tissue/cell damage may involve activation of endogenous CNTF signalling which, by virtue of its catabolic action, has the potential to counteract some adverse effects of obesity and of the associated metabolic syndrome." (PMID 35585213, 2022). "Inhibition of IL6 and SOCS3 and facilitation of CNTF could serve as a favorable strategy to enhance insulin action and improve glucose homoeostasis, which are of importance for treating obesity-related disorders for chickens." (PMID 32106651, 2021). "Collectively, these data lend support to a possible role of CNTF as an insulin-sensitizer, which could be harnessed to overcome obesity-related adipose inflammation and insulin resistance." (PMID 31781039, 2019). "Given that leptin and CNTF play important roles in energy homeostasis and that obesity is an inflammatory condition in adipose tissue, we hypothesized that G-CSF could also play a role in energy homeostasis." (PMID 25144367, 2014). "In contrast to HFD, the hyperphagic obesity of ob/ob mice did not appear to be associated with modifications in CNTF signaling." (PMID 24409114, 2013). "Besides GHRL, the set of causal genes shared by obesity and cachexia comprised ADRB2, MC4R, and CNTF." (PMID 20815942, 2010). "Collectively, these findings suggest that in patients with obesity CNTF signalling is activated in a still unknown tissue/organ and that the peptide is released into the circulation, potentially transducing signals to distant organs and affecting body metabolism." (PMID 35585213, 2022). "Whereas this finding suggests that sex hormones may instigate differential CNTF production and secretion, the higher amount of this metabolically beneficial cytokine may be involved in the lower and later incidence of some obesity-related complications in female patients." (PMID 35585213, 2022). "In all three groups, circulating CNTF was always higher in women than in men; in particular, the median value was about 2.5-fold higher in Control women, more than 3-fold higher in women with obesity, and about 1.5-fold higher in women with obesity and diabetes." (PMID 35585213, 2022). "To establish whether obesity involves activation of endogenous ciliary neurotrophic factor (CNTF) signalling, we evaluated its plasma levels in patients with obesity and correlated its values with the major clinical and haematological indices of obesity, insulin resistance and systemic inflammation." (PMID 35585213, 2022). "Notably, the two patient groups had significantly higher plasma CNTF than Control subjects; however, although patients with obesity and diabetes exhibited a higher median plasma CNTF level than those with obesity alone, the difference was not statistically significant." (PMID 35585213, 2022).
Obesity (continued). "Thus, a greater knowledge of CNTF-mediated regulation of the energy balance may suggest new therapeutic strategies for human leptin-resistant obesity." (PMID 24409114, 2013). "Research shows that CNTF can alleviate MAFLD, as recombinant CNTF improves obesity-related markers, lowers lipid levels, boosts insulin sensitivity, and significantly reduces liver injury and MAFLD in high-fat diet-induced obese rats." (PMID 40969371, 2025). "Similar to CNTF/Axokine, IC7 protected mice from obesity and insulin resistance." (PMID 38569939, 2024). "The results showed that plasma CNTF was significantly higher in males and females with obesity with and without diabetes than in healthy subjects." (PMID 35585213, 2022). "In this observational study, we measured circulating CNTF and CNTFRα in a cohort of patients with obesity with or without diabetes and in age- and gender-matched healthy subjects." (PMID 35585213, 2022). "However, the weight-reducing effect of CNTF was evaluated in normal mice and not in a model of diet-induced obesity (DIO), which resembles most of the key features of the human metabolic syndrome." (PMID 35316287, 2022).
amyotrophic lateral sclerosis (17 papers, 2008 to 2025). Amyotrophic lateral sclerosis (ALS) is a neurodegenerative disease characterized by progressive muscular paralysis reflecting degeneration of motor neurons in the primary motor cortex, corticospinal tracts, brainstem and spinal cord. "Axokine, the recombinant human variant of CNTF, initially entered human clinical trials for the treatment of amyotrophic lateral sclerosis (ALS) but was repurposed to treat obesity and type 2 diabetes when treated patients were observed to lose body weight." (PMID 34576181, 2021). "CNTF signaling aids in the prevention of neuronal degeneration after injury and is neuroprotective in diseases such as multiple sclerosis (MS) and amyotrophic lateral sclerosis (ALS)." (PMID 37417740, 2023). "The few available studies show that CNTF is barely detectable in the blood of healthy subjects, whereas its concentration increases in patients with conditions as diverse as amyotrophic lateral sclerosis, septic shock and autism." (PMID 32528252, 2020). "Given the importance of CNTF function in the central nervous system, it is highlighted as a neurorestorative target for multiple sclerosis, AD, Huntington’s disease, and amyotrophic lateral sclerosis." (PMID 33519417, 2020). "CNTF is essential for the survival of motor neurons, hence has been tested as a therapy for amyotrophic lateral sclerosis (ALS)." (PMID 30555354, 2018). "The first clinical trial with NTFs was the systemic administration of ciliary neurotrophic factor (CNTF) in amyotrophic lateral sclerosis (ALS) patients." (PMID 37047292, 2023). "GDNF supports dopaminergic and motor neuron survival in PD and amyotrophic lateral sclerosis (ALS), while CNTF may promote remyelination and motor/oligodendrocyte viability in ALS and SCI." (PMID 40943142, 2025). "The first neurotrophin clinical trials tested the effects of either brain-derived neurotrophic factor (BDNF) or ciliary neurotrophic factor (CNTF) for amyotrophic lateral sclerosis (ALS), wherein the neurotrophin was administered by subcutaneous (SQ) administration." (PMID 35745855, 2022). "However, amyotrophic lateral sclerosis (ALS) trials with systemic CNTF injections were stopped due to unacceptable side effects, indicating that any manipulation of CNTF signaling in MN diseases will need to be more specifically targeted." (PMID 18588528, 2008).
Stroke (14 papers, 2007 to 2025). Sudden impairment of blood flow to a part of the brain due to occlusion or rupture of an artery to the brain. "Ciliary neurotrophic factor (CNTF) is exclusively expressed in astrocytes; stroke induces upregulation of CNTF." (PMID 35743941, 2022). "The expression of CNTF is rapidly and robustly induced in astrocytes upon brain injury and stroke, where it serves a neuroprotective role, as it does in an experimental autoimmune encephalomyelitis (EAE) model and the retina." (PMID 23693126, 2013). "This is consistent with our finding that CNTF mRNA doubles within one hour after stroke to serve a neuroprotective role." (PMID 23693126, 2013). "Additionally, intracerebral infusion of GDNF promotes striatal neurogenesis after stroke and CNTF has been shown to promote the development of neurons and glial cells and prevent ischemia-reduced neuronal loss in gerbils." (PMID 36076942, 2022). "An NSC might be a type of astrocyte; glial scar formation after injury may partly be due to activated astrocyte-like NSCs differentiating into astrocytes under the control of post-stroke upregulated CNTF." (PMID 35743941, 2022). "Interestingly, overexpression of leucine zipper-bearing kinase (LZK), a positive modulator of astrogliosis, resulted in increased distant axonal sprouting after stroke in the cervical region and increased production of ciliary neurotrophic factor (CNTF) by the surrounding astrocytes." (PMID 39086680, 2023). "Other candidates, such as transforming growth factor β1 (TGF-β1), ciliary neurotrophic factor (CNTF), and lipid phosphate phosphatase-related protein type 1 (LPPR1), have also been reported to contribute to CST axon sprouting after stroke and pyramidotomy." (PMID 40191711, 2025). "In animal models, the neurotrophin ciliary neurotrophic factor (CNTF), which is endogenously upregulated in a stroke onset, mediates the neurogenesis and an anti-inflammatory process." (PMID 28373915, 2017). "Endogeneous or exogenously injected neurotrophic factors including BDNF, GDNF, CNTF and NT3 had neuroprotective effect in damaged brain including stroke." (PMID 18060066, 2007). "In our study, the expression of all analyzed factors, except CNTF, was increased at the 7th or 14th day after transplantation, at a time when, in stroke animals without transplantation, a decrease in the amount of mRNA was observed." (PMID 26607630, 2016).
diabetes (12 papers, 2013 to 2025). "CNTF can reduce the loss of dopaminergic amacrine cells in the early stages of diabetes." (PMID 29795129, 2018). "In STZ-induced diabetic mice, diabetes significantly altered the density and infiltration of DCs, a major source of ciliary neurotrophic factor (CNTF), by disrupting their neural communications." (PMID 41471293, 2025). "In one previous study, streptozotocin (STZ)-induced diabetes reduces the level of ciliary neurotrophic factor (CNTF), an important neurotrophic factor from SCs." (PMID 35795572, 2022). "In summary, we have provided novel data showing efficacy of CNTF, exendin-4, and cyclopentolate in preventing or restoring diabetes-induced depletion of the corneal sub-basal nerve plexus when delivered to the eye." (PMID 35566433, 2022). "Preview studies have also proposed CNTF as a candidate agent for the therapy of diabetes complications." (PMID 34880765, 2021). "Ciliary neurotrophic factor (CNTF) has been evaluated as a candidate therapeutic agent for diabetes and its neural complications." (PMID 29795129, 2018). "This work confirms previous studies demonstrating diabetes-induced reductions in peripheral nerve tissue of cytokines such as IL-6, TNFα and CNTF." (PMID 24152426, 2013). "Based on current understanding of ciliary neurotrophic factor (CNTF)- or diabetes-induced depression of visual function, VEGF might play a role in regulating vision through the fine tuning of phototransduction and visual cycle machineries." (PMID 34356612, 2021).
retinitis pigmentosa (11 papers, 2010 to 2025). Retinitis pigmentosa (RP) is an inherited retinal dystrophy leading to progressive loss of the photoreceptors and retinal pigment epithelium and resulting in blindness usually after several decades. "To elucidate cellular mechanisms underlying CNTF-dependent enhancement of neuronal viability, we have investigated the impact of CNTF signaling on retinal metabolism in a mouse model of retinitis pigmentosa, in which rod death precedes cone loss." (PMID 36396639, 2022). "To understand the molecular mechanism underlying CNTF-mediated neuroprotection, we performed RNA-seq analyses using a well-established preclinical model of retinitis pigmentosa." (PMID 32313077, 2020). "In one phase 1/2 clinical trial, CNTF was administered to patients with retinitis pigmentosa via a slow-release implant in the eye." (PMID 37108642, 2023). "In a long-term follow-up study of a multicenter, sham-controlled trial, eyes of patients with retinitis pigmentosa treated with CNTF (delivered via an intraocular encapsulated cell implant) exhibited greater loss of total visual field sensitivity compared to sham-treated eyes." (PMID 39408817, 2024). "The results of this trial showed that CNTF was generally well tolerated and may have some beneficial effects on visual function in patients with retinitis pigmentosa." (PMID 37108642, 2023). "To decipher CNTF-triggered molecular events in the degenerating retina, we performed high-throughput RNA sequencing analyses using the Rds/Prph2 (P216L) transgenic mouse as a preclinical model for retinitis pigmentosa." (PMID 32313077, 2020). "A phase 1 trial with GDNF and CNTF in patients with retinitis pigmentosa, indicated that CNTF is safe for the human retina, even with severely compromised photoreceptors, and may promote visual improvement." (PMID 22737370, 2010). "In this study, we provide evidence that delivery of the same CNTF used in human trials to a mouse model of retinitis pigmentosa results in a significant change in retinal metabolism, thus revealing a previously unknown cellular mechanism underlying the potent and broad neurotrophic effects of CNTF." (PMID 36396639, 2022).
Alzheimer disease (10 papers, 2013 to 2024). A progressive, neurodegenerative disease characterized by loss of function and death of nerve cells in several areas of the brain leading to loss of cognitive function such as memory and language. "Unlike the ADAM10, which is best taken in the early stages of cognitive impairment, the CNTF can rescue severe and late stages of cognitive impairment in Alzheimer’s disease." (PMID 39588547, 2024). "Also, previously, we described ciliary neurotrophic factor (CNTF) derived peptide mimetics which showed beneficial effects on neurogenesis, synaptogenesis, synaptic plasticity, and cognition in mouse and rat models of Alzheimer’s disease." (PMID 23320097, 2013).
Insulin resistance (9 papers, 2014 to 2024). Increased resistance towards insulin, that is, diminished effectiveness of insulin in reducing blood glucose levels. "Chronic inflammation and increased oxidative stress stimulate insulin resistance and also deprive retinal cells of neurotrophic factors essential for their survival, including insulin, leukemia inhibitory factor, and ciliary neurotrophic factor." (PMID 35476846, 2022). "Some members of the IL-6 family like ciliary neurotrophic factor (CNTF) have been shown to improve insulin resistance and glucose tolerance by activating skeletal muscle AMPK." (PMID 25025664, 2014). "Conversely, CNTF may reduce tissue destruction during inflammatory attacks and confer protection from inflammation-induced insulin resistance in FLHS chickens." (PMID 32106651, 2021). "Made from the combination of two different cytokines (IL-6 and ciliary neurotrophic factor [CNTF]), IC7Fc modifies food intake and body weight and improves insulin resistance, thereby improving metabolic homeostasis in mice." (PMID 36691622, 2023). "GDNF, CNTF, BDNF, and NRG4 improve insulin resistance and alleviate hepatic steatosis by reducing hepatic lipogenesis and improving β-oxidation." (PMID 32175323, 2020). "In women, plasma CNTF showed a moderate correlation with WHR; notably, there was a strong correlation with BMI, the insulin resistance indices fasting insulin and HOMA index and the inflammatory markers hsCRP and IL-6, as well as a very strong correlation with leptin." (PMID 35585213, 2022).